PTH (parathyroid hormone)
Diseases named in the same sentence as PTH in open-access papers (continued):
Sharing a sentence is not in itself a finding about the gene and the disease.
renal osteodystrophy (continued). "Therefore, preoperative serum ALP concentrations generally reflect the extent of bone histologic change in patients with high-turnover lesions of renal osteodystrophy, and values frequently correlate with serum PTH concentrations, as shown in our study." (PMID 33143476, 2020). "However, a considerable proportion of CKD patients who have serum PTH levels within the recommended range still have renal osteodystrophy." (PMID 31637056, 2019). "Other factors than PTH level might regulate osteoblast function in renal osteodystrophy in PD such as high serum glucose, cytokines and local bone growth factors that decrease bone formation making LTBD." (PMID 30524306, 2018). "Furthermore, without bone biopsy, the gold standard of diagnosis, the utility of blood intact parathyroid hormone concentration in the assessment of renal osteodystrophy remains controversial." (PMID 27275607, 2016). "In addition, all patients had meticulous management of their renal osteodystrophy, and the median parathyroid hormone (PTH) level was 1.5-times the upper limit of normal." (PMID 17401584, 2007). "Renal osteodystrophy (ROD) is a bone disorder specifically associated with CKD and is characterised by alterations in bone turnover, mineralisation, volume, linear growth, and strength due to disturbances in calcium, phosphate, parathyroid hormone (PTH), and vitamin D metabolism." (PMID 40298783, 2025). "PTH and alkaline phosphatase are good predictors to differentiate high and low bone turnover disease, whereas DEXA does not discriminate between the histologic and architectural defects that define renal osteodystrophy but seems important in evaluating the risk of fracture." (PMID 36615824, 2022). "Moreover, studies in patients with renal osteodystrophy subjected to bone biopsy have shown an inverse correlation of sclerostin and PTH levels, as well as a negative association with bone turnover." (PMID 36615824, 2022). "Moreover, increased PTH levels may lead to skeletal pain due to renal osteodystrophy." (PMID 41155999, 2025). "Compared with healthy volunteers, these 6 patients with ESRD have significantly elevated serum PTH and FGF23 levels, suggesting the high bone turnover renal osteodystrophy." (PMID 39883525, 2025). "As expected, CKD mice had markedly elevated PTH and FGF23 levels, suggesting the high bone turnover subtype of renal osteodystrophy in this model." (PMID 39883525, 2025). "The intact parathyroid hormone (iPTH) assay is the standard method for measuring the level of PTH in CKD patients and continues to be the most frequently used marker for correlating the clinical diagnosis of renal osteodystrophy or bone disease in CKD cases." (PMID 39606517, 2024). "Vitamin D, parathyroid hormone (PTH), and fibroblast growth factor-23 (FGF-23) are biomarkers of renal osteodystrophy." (PMID 36012420, 2022). "Disorders of vitamin D, PTH, and klotho protein in ESRD lead to the development of distant complications, such as renal osteodystrophy, soft-tissue calcification, and calciphylaxis (calcific uremic arteriolopathy)." (PMID 32823917, 2020). "Renal Osteodystrophy (ROD), the bone component of CKD-mineral bone disorder (CKD-MBD3), is traditionally assessed using histomorphometry, with high turnover bone disease treated by reducing parathyroid hormone (PTH) with calcitriol or calcimimetics." (PMID 39664935, 2025). "Persistent levels of PTH, as in CKD-MBD, lead to the development of renal osteodystrophy." (PMID 38785509, 2024). "The finding that in the face of normal Ca, Pi, calcitriol, and PTH, CKD still produced renal osteodystrophy lead to the hypothesis that renal injury/repair factors released to the circulation produce systemic complications of CKD." (PMID 36776982, 2023). "Interestingly, although exercise prevented trabecular loss, it did not alter serum PTH and FGF23 levels or the number of osteoclasts around trabeculae, suggesting that exercise does not alter the subtype of renal osteodystrophy." (PMID 39883525, 2025).
renal osteodystrophy (continued). "Thus, the expression of sclerostin in jck mouse, a model of progressive kidney disease occurs at early stages of CKD, even before PTH and FGF-23 increase, suggesting that sclerostin may play an early role in the development of renal osteodystrophy." (PMID 36615824, 2022). "Furthermore, the utility of blood intact parathyroid hormone concentration in the assessment of renal osteodystrophy remains controversial without bone biopsy, the gold standard of diagnosis." (PMID 27275607, 2016).
malnutrition (53 papers, 2012 to 2025). Inadequate nutrition resulting from poor diet, malabsorption, or abnormal nutrient distribution. "Studies have shown that CKD–MBD evidenced by high serum levels of phosphate, calcium, CPPs, and PTH and vitamin D deficiency directly causes inflammation, followed by malnutrition/PEW and sarcopenia." (PMID 35353283, 2022). "In some previous studies, correction for indicators of malnutrition and inflammation attenuated the observed association of low PTH states with mortality." (PMID 34959954, 2021). "In some high-risk groups, such as the elderly, malnutrition, and postmenopausal women, PTH has better prospects for fracture treatment." (PMID 31718681, 2019). "Lower PTH level is associated with mortality probably owing to malnutrition, and also associated with adynamic bone disease owing to skeletal resistance to PTH." (PMID 30290781, 2018). "Low bone turnover is also thought to be promoted by reduced PTH secretion caused by nutritional deficiency in diabetic patients." (PMID 23843805, 2012). "In relation to its strong impact on metabolic functions, PTH may also be associated with malnutrition in patients with PHPT, SHPT, and even tertiary hyperparathyroidism." (PMID 40731865, 2025). "Furthermore, malnutrition has been shown to be associated with lower PTH levels and higher mortality among hemodialysis patients, but cannot be depicted with claims data to a sufficient extent." (PMID 36480088, 2023). "Moreover, reduction in serum PTH can prevent PTH-dependent energy expenditure, cachexia, and sarcopenia, thus lowering the risk of malnutrition/PEW." (PMID 35353283, 2022). "Mehrotra indicated that reduced PTH is a risk factor for malnutrition." (PMID 36494810, 2022). "High circulating PTH levels increase the risk for bone fracture, cachexia, and malnutrition/PEW." (PMID 35353283, 2022). "In addition, low PTH or low P is associated with malnutrition or malnutrition-inflammation complex (MIC) in dialysis patients, leading to the increased susceptibility to infections." (PMID 33441921, 2021). "One of the reasons why decrease of PTH is associated with increase of mortality may be malnutrition." (PMID 30290781, 2018). "Nutritional status may be a confounder since it modulates PTH levels and both malnutrition and BMI have been associated to mortality in dialysis patients." (PMID 28339474, 2017). "Moreover, we cannot completely rule out the influence of residual confounders such as inflammation and malnutrition, which are commonly associated with low PTH levels and may also influence clinical outcomes." (PMID 36498703, 2022). "CKD, characterized by a markedly elevated fracture risk, is also known to negatively impact bone health through various mechanisms, including increased parathyroid hormone levels, reduced vitamin D levels, metabolic acidosis, and malnutrition." (PMID 40896277, 2025). "There is substantial evidence suggesting that PTH significantly contributes to the pathogenesis of malnutrition." (PMID 40731865, 2025). "Non-traditional risk factors in CKD include disorders of mineral metabolism, elevated serum PTH levels, excessive intake of calcium supplements, inflammation, malnutrition, and oxidative stress." (PMID 38654817, 2024). "A Japanese study involving over 15,000 dialysis patients reported an increased odds ratio of low PTH (<60 pg/mL) levels in the presence of low serum albumin and urea nitrogen concentrations used as surrogate markers of malnutrition." (PMID 36498703, 2022). "In our study, patients with an AoAC score >2 also were significantly older; had lower serum albumin, low serum hemoglobin and TSAT levels; and elevated serum PTH levels because of malnutrition, inflammation, and atherosclerosis syndrome." (PMID 36561768, 2022). "Low PTH levels can induce inflammation, malnutrition and protein-energy wasting, besides, inflammation can induce suppression of PTH secretion." (PMID 33514340, 2021).
malnutrition (continued). "We believe that our findings give clinically important information about the prevention of fractures in patients undergoing hemodialysis by using not only PTH management, but also malnutrition management." (PMID 34445007, 2021). "The changes in the levels of vitamin 25(OH)D and PTH levels were significantly correlated with malnutrition in CHC patients." (PMID 33884041, 2021). "For patients on dialysis, the higher risk of mortality and vascular outcomes in patients with low levels of PTH has been explained by older age, malnutrition, and poor protein intake." (PMID 29478201, 2018). "Group 0 was excluded because of the relationship between low PTH with aging and malnutrition." (PMID 36176632, 2022). "Further research is needed to confirm whether intervention to reduce PTH levels can serve as an effective treatment for malnutrition and PEW in CKD patients." (PMID 35573870, 2022). "Studies found that age, decline in mobility, malnutrition, decreased muscle strength, lower bone mineral density, abnormal vitamin D metabolism, abnormal parathyroid hormone level, cardiovascular disease, and pneumonia contributed to mortality after hospitalization in hemodialysis subjects." (PMID 26149489, 2015). "Notably, PTH level was an independent predictor of malnutrition." (PMID 36839171, 2023). "In this study, CHC patients with moderate and severe malnutrition ASG score showed a significant decline in vitamin D and an increase in PTH levels, especially in CHC patients who received inadequate amounts of vitamin D and Ca in their foods." (PMID 33884041, 2021). "CHC patients with moderate and severe malnutrition SGA scores showed a significant decline in the levels of vitamin D, increased PTH, and lower values of HGS and muscle mass indices compared to well-nourished patients and control subjects." (PMID 33884041, 2021). "While there are currently effective medications available for regulating calcium-phosphate and PTH levels, there is a lack of effective drugs for improving malnutrition symptoms." (PMID 38328574, 2023). "The degree of significant fibrosis and cirrhosis correlated positively with adiposity, lower vitamin 25(OH)D, and increased levels of PTH, diet scores, and vitamin D and Ca intake and negatively with SGA malnutrition scores, HGS, and muscle mass indices (MAC, TSF, and MAMC, respectively)." (PMID 33884041, 2021).
uremia (50 papers, 2005 to 2025). A clinical syndrome associated with the retention of renal waste products or uremic toxins in the blood. "Among the complex endocrine changes associated with uremia, we observe that parathyroid hormone gene (PTH) expression is enhanced, consistent with the elevated hormone levels observed." (PMID 23809614, 2013). "Uremia, PTH and phosphate were already implicated in the cardiac remodeling process in CKD43." (PMID 30787343, 2019). "In addition to high PTH levels, resolution of uremia post-transplant is also associated with a decrease in skeletal resistance to PTH." (PMID 30109232, 2018). "High levels of PTH have been implicated in several complications associated with uremia." (PMID 20886005, 2010). "High/low serum calcium, high PTH, low serum sodium, high white blood cell count, previous occurrences of cerebrovascular events, polycystic kidney disease (as a primary disease), and the use of anticoagulants are independent risk factors for hemorrhagic stroke in hemodialysis patients with uremia." (PMID 37250421, 2023). "PTH is influenced by multiple factors (vitamin D status, calcium and phosphate balance, renal function, degree of uremia, acid–base status, age, etc.)." (PMID 41303180, 2025). "Enhanced bone reactivity to PTH due to improved uremia symptoms and the effects of high PTH on a functional kidney graft can lead to increased serum calcium levels." (PMID 37183797, 2023). "In the clinical situation, the majority of patients with SHPT will, despite previous long-term uremia, present a significant fall in plasma PTH after kidney transplantation." (PMID 36267284, 2022). "It is believed that overexpression of sclerostin in bone cells because of uremia plays an important role in the low turnover of bone despite a high PTH concentration." (PMID 35220856, 2022). "The dietary adenine administration induced a stable and similar degree of chronic uremia in DBA2/N mice with an increase of uremia blood markers such as blood urea nitrogen, calcium, creatinine, alkaline phosphatase, and parathyroid hormone." (PMID 35916902, 2022). "In uremia circulating PTH is necessary for generating the increase in FGF23 expression in bone and the high plasma levels of FGF23, as shown in experimental studies by us and others." (PMID 33233840, 2020). "Secondly, the majority of our patients were at CKD stages 4 and 5 at which the deranged metabolic axis of calcium-phosphate-PTH/FGF23 is well established as are the atherosclerotic changes driven by the progression of uremia." (PMID 32571327, 2020). "Normally, FGF23 decrease PTH gene expression and parathyroid cell proliferation 64, 65, however, hyperplastic parathyroid glands in uremia patients resist to FGF23 inhibitory action due to low expression of both klotho and FGF 23-receptor complex 66-68." (PMID 31839746, 2019). "Renal dysfunction, due to chronic hypoperfusion, increases P retention and 25(OH)D activation disturbance (decreased activity of renal 1-alpha-hydroxylase induced by uremia), which stimulates PTH secretion." (PMID 29599854, 2018). "High levels of PTH in uremia also affect the metabolism and function of B cells, as well as T-lymphocyte functions contributing to changes in cellular immunity." (PMID 23202302, 2012). "They demonstrated that the significantly elevated plasma levels of PTH in uremia became normal within one week of the kidney transplantation." (PMID 23094155, 2012). "Thus, despite very high circulating PTH levels, end-organs like bone sometimes respond less robustly than expected in uremia—a paradox attributable to receptor desensitization and the accumulation of inhibitory PTH fragments." (PMID 41227247, 2025). "Interestingly, parathyroid hormone secretion decreased significantly after reversal of uremia by homogeneic renal transplantation, while the expression of CaSR and VDR genes in parathyroid glands remained decreased." (PMID 36267284, 2022).
uremia (continued). "Non-classical risk factors (uremia-related factors) such as serum phosphate, calcium phosphate product, and intact parathyroid hormone (i-PTH) were significantly related to arterial calcification in HD patients." (PMID 29558928, 2018). "Conversely, in our research most of the uremia rats these exhibit arterial medial calcification had secondary high PTH level which may contributed to the increased serum RANKL and OPG level." (PMID 24330832, 2013). "Chronic excess of PTH in uremia affects PMNL functions via sustained elevation of their [Ca2+]i." (PMID 23202302, 2012). "The current study shows that PTH suppression is not linked to endothelial function improvement in the uremia rat since cinacalcet, a calcimimetic, does not show a significant effect on improving endothelial function although it suppresses PTH effectively." (PMID 20169119, 2010). "While patients with advanced renal disease often have elevated levels of PTH, the relevance of a possible stimulatory effect of uremia on PTH synthesis remains undefined, as patients with renal disease have other abnormalities that might contribute to PTH elevation." (PMID 36246903, 2022). "Excessive PTH may also play a role in extraskeletal manifestations of uremia." (PMID 28445401, 2017). "Its pathogenesis is driven by disordered homeostasis of vitamin D, parathyroid hormone (PTH), calcium, phosphate, acid–base balance, and progressive uremia." (PMID 41303180, 2025). "Meanwhile, recent studies revealed that suppression of PTH by CINA markedly attenuates vascular remodeling and calcification in uremia." (PMID 39165274, 2024). "Uremia was induced by subtotal renal ablation, and serum levels of BUN and PTH were significantly elevated four weeks after the second renal surgery." (PMID 26955758, 2016). "Parathyroid hormone (PTH) is normalized despite low levels of CaR and VDR after experimental reversal of uremia." (PMID 23094155, 2012). "Parathyroid hormone (PTH) rises early in CKD and is a culprit contributor to its uremia toxicity." (PMID 36304157, 2022). "In our in vivo study, after 14 weeks of the induction of 75% renal mass reduction and the development of mild uremia with increases in BUN, PTH and renal levels of ADAM17 (an enzyme that increases in kidney disease of all etiologies), no changes in serum Ca or P levels were observed." (PMID 35807767, 2022). "There is an increasing resistance to PTH signaling in uremia and so higher plasma levels of PTH is needed to maintain normal bone turnover and plasma calcium." (PMID 34940607, 2021). "Calcitriol continues to stimulate FGF23 expression in uremia and so treatment with active vitamin D analogs in CKD patients may not only target PTH levels but also unwanted FGF23 expression in bone." (PMID 33233840, 2020). "Under physiological conditions FGF23 inhibits PTH secretion and production; however, in uremia, FGF23 fails to inhibit PTH release because of downregulation of the parathyroid FGFR1/Klotho complex." (PMID 30909513, 2019). "Surprisingly, in uremia, concomitantly elevated FGF23 and PTH levels are observed." (PMID 29063159, 2018). "Somerville and Kaye found that 1,25D ameliorated PTH resistance in chronic but not acute renal failure; in contrast, phosphate was the agent of resistance when uremia was created by intravenous infusion of urine from intact kidneys." (PMID 28445401, 2017). "Taken together, our results on NX rats and the results from AKI models suggest that PTH signaling is not necessary for the early skeletal response to acute uremia." (PMID 25885328, 2015). "Ten weeks of uremia increased serum PTH levels, while treatment with 2%La did not suppress this at 10th week (1643 ± 115 mmol/L)." (PMID 24330832, 2013). "Our results demonstrate that uremia significantly compromises endothelial function while paricalcitol improves endothelial function in uremic rats in a dose-dependent manner independent of serum PTH levels or blood pressure." (PMID 20169119, 2010).